TNF (tumor necrosis factor)
Diseases named in the same sentence as TNF in open-access papers (continued):
Sharing a sentence is not in itself a finding about the gene and the disease.
colitis (continued). "paracasei L9 expressing Amuc_1100 protein, mRNA levels of pro-inflammatory cytokines (IL-6, TNF-α, and IL-1β) and anti-inflammatory cytokines (IL-4 and IL-10) were measured in colon tissues of DSS-induced colitis mice." (PMID 41515240, 2025). "MOR agonists have been demonstrated to alleviate colitis in preclinical models of IBD by dampening inflammatory cytokine production, including TNF-α, while chronic opioid use in IBD patients correlates with adverse clinical outcomes." (PMID 40564117, 2025). "Research indicates that BDVs suppress the production of inflammatory cytokines like TNF-α, IL-17A, and IFN-γ in experimental colitis models." (PMID 40648712, 2025). "As expected, induction of colitis with DSS triggered a strong pro-inflammatory response, evidenced by significant upregulation of TNF-α, IL-6, and IL-17 expression." (PMID 40869289, 2025). "The upregulation of pyyb and y8b observed in infected tilapia resembled findings in rodent colitis models, where NPY expression was induced by pro-inflammatory mediators such as TNF-α and IL-1β." (PMID 41007974, 2025). "Studies in murine DSS-induced colitis models show that CST treatment significantly reduced colonic levels of pro-inflammatory cytokines such as IL-1β, IL-6, IL-18, and TNF." (PMID 40370467, 2025). "Mechanistically, L. curvatus DCF0620 treatment controlled the infiltration of cells that express pro-inflammatory cytokines (TNF-α, IL-1β, IL-6, and IL-17) and fibrotic markers (TGF-β, Col1, and α-SMA) into the intestinal tissue of DSS-induced colitis mice." (PMID 41567191, 2025). "The present study demonstrated that SS18‐50‐H treatment resulted in a reduction in mRNA expression of TNF‐α, COX‐2, IL‐10, and IL‐6 to levels within the normal range in colitis mice." (PMID 39803293, 2025). "In models of dextran sulfate sodium (DSS)-induced colitis, Akkermansia muciniphila (AKK) demonstrated protective effects by decreasing inflammatory cytokines (TNF-α, IL-1β, IL-6) and inhibiting NLRP3 inflammasome activation." (PMID 40299512, 2025). "The administration of L. paracasei strains (KBL382, 384, 385) demonstrated protective effects in DSS-induced colitis models, with L. paracasei KBL382-treated mice showing reduced levels of pro-inflammatory cytokines, including IL-4, IL-6, TNF-α, and IL-17a." (PMID 40243712, 2025). "Macrophage TIM3 can inhibit the expression of proinflammatory cytokines such as TNFα, IL-1β, IL-6, IL-12, and NOS2 in dextran sodium sulfate (DSS)-induced colitis." (PMID 41307843, 2025). "Heat-killed Companilactobacillus crustorum MN047 substantially reversed TNF-α and IL-6 in DSS induced colitis mice." (PMID 40219029, 2025). "Another study tested the efficacy of a monoclonal anti-mature IL-18 antibody in DSS colitis mice found that it improved acute and chronic DSS colitis, reduced production of IFNγ and TNFα and ameliorated the epithelial cell barrier." (PMID 40642091, 2025). "They observed an increase in anxiety-like behaviours and features of colitis including colon shortening, increased Myeloperoxidase (MPO) activity and Tumour Necrosis Factor (TNF) Alpha expression." (PMID 41462928, 2025). "Suramin treatment significantly reduced plasma PTX3, TNF-α, NETs, and MDA levels, and colonic TNF-α and VEGF concentrations compared to the untreated colitis group." (PMID 40428786, 2025). "In this study, we demonstrate that Sal directly binds to TNF-α, and this interaction is critical for its inhibition of IKK/NF-κB signaling and its overall efficacy in mitigating experimental colitis." (PMID 41296400, 2025). "In colitis mice, the CCFM1426 and VA combination significantly reduced IL-6 and TNF-α levels whilst increasing IL-10 levels (p < 0.05)." (PMID 40777179, 2025). "In mice with colitis, PYY3–36 alleviates colonic inflammation by reducing myeloperoxidase activity and lowering both colonic and systemic levels of TNF-α and IL-6." (PMID 40723884, 2025).
colitis (continued). "The therapeutic effect of SPSs on colitis was investigated by trinitrobenzene sulfonic acid (TNBS)-induced rats model, TNF-α-stimulated Caco-2 cells, LPS-induced THP-1 cell model, and a co-culture model of Caco-2 and THP-1." (PMID 41008172, 2025). "In the DSS colitis model, TLR4/MyD88 signaling consistently activates the IKK-NF-κB axis, thereby driving TNFα expression, potentially bypassing any inhibitory effects exerted by Bcl6." (PMID 40416976, 2025). "In dysbiosis, certain commensals act as pathobionts, triggering pro-inflammatory responses, as seen in experimental colitis, where H. hepaticus activates TH17 cells through IL-17, IL-23, and tumor necrosis factor (TNF)-α." (PMID 40585846, 2025). "Macrophages are critical immune cells involved in Colitis, with IFN-γ, TNF-α, and microbial products like LPS stimulating their M1 polarization." (PMID 41008172, 2025). "Wedelolactone markedly reduced the IL-1β-induced expression of COX-2, iNOS, TNF-α, and IL-6 in human chondrocytes by inhibiting NF-κB activation and further attenuated colonic inflammation in DSS-induced colitis via suppression of the IL-6/STAT3 axis." (PMID 41304898, 2025). "DSS-induced colitis is characterized by elevated MPO activity, pro-inflammatory cytokines (TNF-α, IL-6, IL-1β), and lipid peroxidation, alongside depleted antioxidant defenses (SOD, CAT, GSH)." (PMID 41395463, 2025). "A significant increase in the production of pro-inflammatory cytokines (e.g., IL-1β, TNF-α, and IL-6) by macrophages was observed in the dextran sodium sulfate (DSS) colitis mouse model." (PMID 40508145, 2025). "Similar intervention outcomes were observed in patients with colitis, with EEN reducing serum IL-6, interleukin 1 (IL-1), and TNF-α levels and attenuating the state of intestinal oxidative stress." (PMID 41393952, 2025). "RT-PCR analysis revealed that the expression levels of three genes, including IL-6, TNF-α, and TGF-β, in the colon tissue of the colitis group were higher than those of the control group." (PMID 40896701, 2025). "Arbutin has been reported to significantly down-regulate the levels of inflammatory cytokines (IL-1β, IL-6, and TNF-α), iNOS, and cyclooxygenase-2 (COX-2) in colitis mice." (PMID 40078988, 2025). "Our observations indicated that muscone downregulated the expression levels of proinflammatory cytokines, including IL-1β, IL-6, TNF-α, IL-17, and IL-33, in DSS-induced colitis." (PMID 40452925, 2025). "Limonin reduced the generation of proinflammatory cytokines TNF-α, IL-1β, and IL-6 as well as the expression of inflammatory proteins COX-2 and iNOS in the colonic tissues of mice with DSS-induced colitis." (PMID 40078988, 2025). "The results show that HFO reduces the intensity and extent of colitis in rats by regulating the release of MPO and TNF-α, which has a protective effect on the mucosa." (PMID 40656621, 2025). "A recent study demonstrated that Amuc_2109 reduces the levels of TNF-α, IL-1β, and IL-6, as well as NLRP3 expression, while enhancing intestinal barrier function and improving DSS-induced colitis." (PMID 40028328, 2025). "Compared to the MOD group, varying doses of COP treatment significantly reduced the elevated serum levels of TNF-α, IFN-γ, and IL-6, thereby effectively preventing the development of colitis in mice." (PMID 40053041, 2025). "The present investigation observed notably elevated pro-inflammatory cytokine levels (TNF-α, IL-6, and IL-1β) in the colon of mice with DSS-induced colitis." (PMID 39699220, 2025). "Our previous study demonstrated a significant elevation of IL-6, TNF-α, IL-1β, IL-17, IFN-γ and MCP-1 in colitis and showed that activation of the CB2 receptor by HU308 significantly reduces these cytokine levels." (PMID 40005963, 2025). "In both acute and chronic colitis models, vehicle-treated mice showed a significant increase in pro-inflammatory cytokines, IL-6, IL-1β, MCP-1, and TNF-α, compared to healthy controls, which was markedly attenuated by the combination therapies." (PMID 40869234, 2025).
colitis (continued). "The study found that CW notably reduced the mRNA levels of pro‐inflammatory markers including TNF‐α, IL‐1β, IL‐6, Toll‐like receptor 4 (TLR4), and iNOS, while it enhanced the expression of the anti‐inflammatory cytokine IL‐10 in colitis." (PMID 39830908, 2025). "In female rats, estrogen and progesterone reduced the production of macrophage migration inhibitory factor (MIF), which promotes tumor necrosis factor (TNF)-alpha and interleukin-1β (IL-1β) expression in early colitis." (PMID 40636118, 2025). "G. lemaneiformis suppressed TNF-α, IL-1β and IL-6 levels in dextran sulphate sodium (DSS)-induced colitis in Balb/c mice and IEC-6 cells, improving intestinal barrier function and microbiota structure, thus preventing intestinal inflammation." (PMID 40077614, 2025). "We also showed that culturing UC lamina propria mononuclear cells (LPMCs) with NETs resulted in enhanced production of TNF-α and IL-1β, and inhibition of NET release attenuated DSS-colitis in mice." (PMID 41194916, 2025). "At the molecular level, proinflammatory cytokines, including tumor necrosis factor-alpha (TNF-α), interleukin-6 (IL-6), interleukin-1β (IL-1β), and interleukin-17 (IL-17) are key mediators in colitis pathogenesis." (PMID 40572721, 2025). "In parallel with these findings, garlic-derived exosome-like nanovesicles suppressed IL-6, IL-1β, TNF-α, and IFN-γ levels, TLR4 and Myd88 pathways in LPS-treated Caco2 cells, and the dextran sulfate-treated mouse colitis model." (PMID 40149930, 2025). "Counter therapies with agents such as infliximab that block inflammatory cytokines, i.e., TNF-α, are being tested to prevent ICI-induced colitis." (PMID 41008842, 2025). "PPI analysis revealed that these compounds effectively modulate inflammatory pathways, particularly IL‐6 and TNF, with significant reductions observed in DSS‐induced colitis models." (PMID 41164267, 2025). "It is well known that pro-inflammatory factors such as TNF-α, IL-1β, IL-6, and IFN-γ play important roles in colitis progression." (PMID 40529132, 2025). "We further measured the production of pro-inflammatory cytokines, TNF-α, IFN-γ, IL-6, IL-1β, and IL-17 in colonic tissue of colitis mice." (PMID 39085655, 2024). "The results showed that ZSS polysaccharide (20 mg/kg) significantly improved the severity of colitis in colitis rats and inhibited the inflammatory response by reducing the activity of TNF-α, IL-1β, IL-6 and MPO in colitis rats." (PMID 39679366, 2024). "For example, L-fucose inhibits macrophage M1 polarization, inactivates the NLRP3 inflammasome, and decreases the levels of TNF-α, IL-1β, and IL-6 in mice with DSS-induced colitis." (PMID 38596683, 2024). "Infliximab, a monoclonal antibody-targeting tumor necrosis factor α (TNF-α), has elicited remission rates of up to 71% in cases of corticosteroid-refractory colitis." (PMID 39311981, 2024). "Anti-TNF-α agents like infliximab ameliorate DAI and histological score in DSS-induced colitis mouse models and induce clinical remission and mucosal healing in UC patients." (PMID 38354108, 2024). "Quercetin can alleviate inflammation by reducing the levels of TNF-α, IL-1β, IL-6, and IL-10, thus treating DSS-induced colitis in mice." (PMID 38902425, 2024). "In our previous study, we found that CD4+ Treg-of-B cells can alleviate the intestinal inflammation and suppress Th1 and Th17 cytokines IFN-γ, TNF-α, and IL-17 in CD4+CD45RBhi T cell-induced colitis through an IL-10-independent mechanism." (PMID 39085655, 2024). "In our experimental study, we observed a significant increase in the mRNA expression levels of pro-inflammatory cytokines, including IL-1β, IL-6, and TNF-α, following DSS administration, indicative of colitis induction in mice." (PMID 38760355, 2024). "The mRNA expression of proinflammatory cytokines in colonic tissues, including IL-1β, IFN-γ, and TNF-α, were decreased in DSS-induced colitis mice treated with NI1 and TJ5 as compared to mice solely treated with TJ5." (PMID 38946731, 2024).
colitis (continued). "As previously reported, Zanthoxylum peel extract can inhibit the expression of TNF-α, IL-1β, and IL-12 by regulating TLR4 and TLR4-related pathways in experimental colitis induced by DSS in mice and LPS-induced inflammation in J774.1 cells." (PMID 39519671, 2024). "Previous studies have revealed that canine MSCs primed with pro-inflammatory cytokines, such as a combination of IFN-γ and TNF-α or TNF-α alone, can significantly enhance their immunomodulatory effects in colitis models." (PMID 39595338, 2024). "In TNBS-induced colitis and OCT administration, a reduction in TNF-α expression and inducible NOS (iNOS) activity was observed." (PMID 38540191, 2024). "The results demonstrated that SP decreased mRNA levels of IL-6, TNF-α, IL-17A, and IL-1β, but enhanced the mRNA level of IL-10 in mice with DSS-induced colitis." (PMID 38725846, 2024). "We estimated the effect of XYKJP on inflammatory cytokines in colitis tissues and found that XYKJP treatment led to a reduction in the levels of IL-1β, TNF-α, and IL-6, and a significant improvement in the level of IL-10 and IL-22, as demonstrated by ELISA." (PMID 39133435, 2024). "L-theanine suppressed the expression levels of TNF-α, IL-1β, IL-6, iNOS, and COX-2 in DSS-induced colitis, and relieved phosphorylation of GSK-3β and Akt/mTOR in Cd-induced ICR mice." (PMID 39572022, 2024). "Oral administration of bilberries reduced disease severity and inflammation in both acute and chronic DSS-induced colitis mice, decreasing IFN-γ and TNFα secretion." (PMID 39494333, 2024). "TPC inhibition or knockdown in mice was shown to increase the number of regulator T (Treg) cells in a transmembrane TNF/TNFR2 dependent manner, contributing to anti-inflammatory effects in a murine colitis model." (PMID 39867224, 2024). "sSIGLEC9 decreased IL-8 and TNF-α gene expression in stimulated COLO 205 and RAW 264.7 cells, alleviating colitis in mouse models." (PMID 39727942, 2024). "In another study using a DSS-induced colitis model, C57BL/6 mice fed an 8% (w/w) fish oil diet showed increased TNF-α mRNA expression and inflammatory cell infiltration in the colonic mucosa." (PMID 39652552, 2024). "In an in vivo study, Kumujan B inhibited the expression of IL-1β, IL-6, and TNF-α and improved the colon barrier function in dextran sulfate sodium salt (DSS)-induced experimental mice colitis." (PMID 39148547, 2024). "CPP1-2-1, on the other hand, reduces the expression of TLR4, NF-κB, TNF-α, and IL-6 in LPS-induced RAW264.7 cells in a dose-dependent manner and alleviates DSS-induced pathological injury in mice with colitis." (PMID 39202931, 2024). "Bacteroides fragilis has been shown to activate TLR2/IL‐10 signaling and reduce levels of tumor necrosis factor alpha (TNF‐α) and IL‐1β, thereby ameliorating dextran sodium sulfate (DSS) induced colitis." (PMID 39073297, 2024). "Furthermore, in vivo (experimental murine colitis model) and in vitro (intestinal epithelial cells) studies both reconfirmed the anti-inflammatory properties of statins by blocking the activity of NF-κB, inhibiting the phosphorylation of IκB and eventually lowering the expression of TNF-α." (PMID 38730498, 2024). "Cinnamic acid administration at doses of 25 and 50 mg/kg resulted in reduced levels of TNF-α and IL-6 in mice with DSS-induced colitis." (PMID 38732594, 2024). "Takahashi found a decreased concentration of serotonin, damage of the myelination, increased tumor necrosis factor-α (TNF-α) and interleukin-6 (IL-6), and depressive-like behavior in DSS-induced colitis." (PMID 38393047, 2024). "MPO, MDA, TNF-α, and IL-6 levels were elevated in the Colitis group but significantly reduced in the DHA-treated group (p < 0.001 for MPO, MDA; p < 0.05 for TNF-α and IL-6)." (PMID 39105785, 2024). "Adoptive T cell colitis in PBS-treated mice predictably led to significantly increased expression of IL-6 and TNF mRNA in the colonic mucosa as compared to naïve WT mice or Rag2−/− sham controls." (PMID 39771552, 2024).
colitis (continued). "At the level of mRNA, the relative expression of TNFα, IL1β, IL6, MMP9, and PTGS2 increased significantly in DSS-induced colitis compared with the control group." (PMID 39064786, 2024). "Specifically, the levels of TNF-α, IL-1β, IL-6, IL-10, IL-2, and IL-12 SOD, CAT, GSH-Px, and MDA were modulated in rats with colitis, also inhibiting TLR4/NF-κB pathway activation." (PMID 39494333, 2024). "The severity of the colitis was evaluated by body weight, colon length, DAI score, HE staining and expression of TNF-α and IL-6." (PMID 38243324, 2024). "Conversely, the administration of GM-CSF has been demonstrated to suppress inflammatory cytokines such as IL-1 and TNFα by upregulating type I interferon, consequently ameliorating the severity of DSS-induced colitis." (PMID 39379604, 2024). "Macrophages express the pro-inflammatory cytokine TNF-α while neutrophils play a role in the development and maintenance of intestinal inflammation and occur in increased numbers during DSS-induced colitis." (PMID 39255739, 2024). "In the present study, the behavior of TNF-α and IL-10 in the blood of a mouse model of DSS-induced colitis was similar to that previously reported." (PMID 38542428, 2024). "Rosiglitazone treatment improved colitis, decreased MPO activity, and decreased the expression of TNF-α and ICAM-1 at the mRNA level." (PMID 39451206, 2024). "Colonic mRNA of both ICI-colitis and IBD patients have exhibited an upregulation of the IFNγ, IL-17 effector pathways and TNF compared to healthy colons." (PMID 39247203, 2024). "Inflammatory factors such IFN-γ, TNF-α, and IL-1β can induce the expression of GBP5; these cytokines are highly expressed in IBD and in the experimental mouse models of colitis." (PMID 39062588, 2024). "ELISA results indicated that DSS-induced colitis mice administered with PSPRS showed higher IL-10 and IgA levels but lower TNF-α, IL-1β, and IL-6 levels." (PMID 38611336, 2024). "Meanwhile, Bacteroides vulgatus can also reduce the expression of colon TNF-α, IL-1β and IL-6 induced by DSS and improve colitis in mice." (PMID 39003416, 2024). "The carbohydrate-rich component of L. edodes polysaccharides suppressed TNF-induced cell death of Caco-2 cells in a dose-dependent manner by inhibiting pMLKL-mediated necroptotic cell death, thus counteracting DSS-induced colitis in mice." (PMID 39840043, 2024). "The increased production of TNFα and IFN-γ by CD1d-independent NK1.1+CD8+ T cell populations can facilitate the pathophysiology of colitis." (PMID 39201260, 2024). "TPC inhibition or knockdown increases the number of regulator T cells in a transmembrane TNF/TNFR2 dependent manner, contributing to anti-inflammatory effects in a murine colitis model." (PMID 39867224, 2024). "A previous study confirmed an improvement in colitis by OXY treatment in a mouse model and downregulation of TNF-α by OXY treatment." (PMID 39548434, 2024). "In addition, one study also found that fermented wild ginseng could relieve the symptoms of colitis in a DSS-induced colitis animal model through inhabiting secretion level of proinflammatory cytokines (IL-1β, IL-6, IL-12, p40, TNF-α, and IFN-γ) and blocking NF-κB signaling pathway." (PMID 38698858, 2024). "↓ TNF-α, IL-6, CCL2, collagen 3A1, intestinal wall thickness, clinical colitis, tissue damage score, rectal inflammation and bleeding score, mast cell number, and degranulation in the proximal colon." (PMID 39519465, 2024). "Purslane extracts have also been shown to inhibit the levels of pro-inflammatory cytokines (TNF-α, 1L-1β, and IL-6) in mice suffering from dextran sodium sulfate (DSS)-induced colitis." (PMID 39845784, 2024). "After coculture with HT and LPS for 24 h, HT (100, 200, 400 μM) significantly decreased TNFα and IL6 in the supernatant of LPS-treated cells, which indicated that HT inhibited the inflammation of colitis in vitro." (PMID 39064786, 2024).